MMP9 (matrix metallopeptidase 9)
Diseases named in the same sentence as MMP9 in open-access papers (continued):
Sharing a sentence is not in itself a finding about the gene and the disease.
aneurysm (continued). "With respect to abdominal aortic aneurysms, the gelatinases MMP-2 and MMP-9 have been found to be overexpressed in the aneurysm wall." (PMID 33573220, 2021). "A key source of MMP9 is infiltrating macrophages, and aneurysms form in MMP9 knockout mice after infusion of mouse bone marrow cells with the MMP9 gene." (PMID 34567206, 2021). "MMP-9 correlates with increasing aneurysm diameter, and its level is elevated in the circulating plasma of patients with AAAs." (PMID 34123662, 2021). "MMP-2 is increased in small aneurysms (<5.5 cm), whereas MMP-9 is dominant in large aneurysms (5.5–7 cm)." (PMID 31963569, 2020). "In line with the previous studies, we observed that the enhanced expression and activation of MMP-9 were closely associated with augmented aneurysm formation, indicating the crucial involvement of MMP-9 in aneurysm formation." (PMID 33239616, 2020). "Intriguingly, MMP-9 expression was found to be correlated with aneurysm diameter (over 5 cm), implying a role for this MMP in later stages of the pathology." (PMID 31390798, 2019). "Several factors related to aneurysm susceptibility (including angiotensin II and nicotine) cause the upregulation of MMP-2 and MMP-9 through aberrantly induced HIF 1-alpha and promote aneurysmal progression." (PMID 31703088, 2019). "Because of its capacity of degrading multiple extracellular components in aortic wall, matrix metalloproteinase 9 (MMP9) has been involved in aneurysm formation." (PMID 30922233, 2019). "A trend for higher MMP-9 values was seen in Loeys-Dietz syndrome, other congenital heart diseases, other aneurysms and dissection < 50 years-old, and Turner syndrome (p = 0.07, Kruskal-Wallis analysis)." (PMID 30883599, 2019). "Herein, we show that blockade of IL-12p40 in the early phase of aneurysm development suppresses macrophage expansion, inflammatory cytokine and MMP-9 production and mitigates AAA development." (PMID 31320700, 2019). "On the contrary, neither Hovsepian nor Eugster had observed a significant correlation between serum MMP9 and aneurysm size of AAA." (PMID 30373522, 2018). "Increased NGAL in aneurysm tissue modulates the activity of MMP-9, protecting it from degradation and thus aiding aneurysm progression." (PMID 29342213, 2018). "Trial dataindicate that both MMP-2 and MMP-9 should be available and active formaximum progression of the aneurysm, suggesting a synergistic andco-dependent relationship between no less than two of the most essentialproteases active in AAA disease." (PMID 28832801, 2017). "According to the statistically strong correlation between mRNA, protein levels of MMP9, and aortic diameter, we suggest that MMP9 expression was shown to be directly dependent on aneurysm diameter." (PMID 29158612, 2017). "In our current and earlier studies, the increase in IL-1β and TNF-α and the imbalance between MMP-9 and TIMP-2 were associated with aneurysm rupture in ovariectomized aneurysm rats." (PMID 28969701, 2017). "In ScNJ mice, the protein expression of receptor for advanced glycation end product (RAGE), another HMGB1 receptor that promotes macrophage inflammation and MMP-9 production during aneurysm development, was also decreased in comparison with ScSnJ mice." (PMID 26741694, 2016). "The role of MMP-9 has been particularly studied by our team and the development of an animal model of aneurysms in rabbits helped to understand the molecular mechanisms involved in the pathology and therefore consider therapeutic strategies." (PMID 26110102, 2015). "Later work in rat and mouse models of IA indicated that macrophage infiltration and MMP expression were associated with aneurysm formation, with specific demonstration of MMP-2 and MMP-9 activity." (PMID 25922566, 2015). "Matrix metalloproteinase-9 (MMP-9) is a zinc endopeptidase contributing to calcium chloride-induced aneurysm development in mice." (PMID 25883602, 2015).
aneurysm (continued). "Because excessive elastolysis mediated by MMP-9 is considered a critical step in aneurysm development, we determined the degree of medial elastin disruption in the CaCl2+PBS and CaCl2+decorin groups." (PMID 25781946, 2015). "We have documented a significant correlation between age, median size of aneurysms, and plasma levels of both MMP-9 and neutrophil gelatinase-associated lipocalin (NGAL) in both central and peripheral aneurysms." (PMID 25866513, 2015). "Immunohistochemical localization showed that the particular enzymes associated with aneurysms were plasmin, MMP-2, MMP-9, and MT1-MMP (an activator of MMP2)." (PMID 25922566, 2015). "The co-culture of GFs with AA lesions shows increased expression of TIMP-1, the inhibitor of the aneurysm severity marker MMP-9." (PMID 26110102, 2015). "TLR4 expression is apparently upregulated in the endothelial cell layer and adventitia of aneurysm walls, and increases MMP9 expression in macrophages, which promote aneurysmal formation." (PMID 23844137, 2013). "The SPARC, MMP-2 and MMP-9 protein expression levels in aneurysms were investigated by immunohistochemistry, western blot and correlative analysis of their expression levels with clinicopathologic factors was performed." (PMID 23516489, 2013). "We observed qualitatively the immunohistochemical staining of SPARC, MMP-2 and MMP-9 for each aneurysm and control artery and assigned each protein a grade ranging from negative staining to extensive staining in intimal and medial smooth muscle cells." (PMID 23516489, 2013). "In this paper, we reported a cohort of patients diagnosed as intracranial aneurysms with obviously increase of SPARC, MMP2 and MMP9 in their pathological aneurysm tissue." (PMID 23516489, 2013). "Blockade of IFN-γ action results in IL-4 driven inflammation, directly increases expression of MMP-9 and -12 leading to aneurysm formation." (PMID 24358274, 2013). "In the mouse genetic model, whereas either MMP-2 or MMP-9 deficiency is resistant to aneurysm formation, disruption of TIMP-1, an MMP-9 inhibitor, leads to exaggerated aneurysm growth." (PMID 22187650, 2012). "Higher MMP-8 and MMP-9 levels were detected in the convex aortic sites than in the concave aortic sites of BAV patients with aneurysms ≤54 mm in diameter." (PMID 22645456, 2012). "MMP-9 has also been found in the aneurysm vessel wall which primarily colocalized with infiltrated macrophages." (PMID 22448249, 2012). "MMP-2 is expressed in most cerebral aneurysms, whereas MMP-9 is expressed primarily in aneurysms with atherosclerotic changes." (PMID 22999528, 2012). "Importantly, the downregulation of angiogenic and matrix-degrading genes such as VEGF, MMP-2, MMP-9, HMGB1, and NF-κB p65 further supports its role in mitigating ECM destabilization and inflammatory amplification—hallmark events in aneurysm pathogenesis." (PMID 40868841, 2025). "In vascular tissues, MMP-9-mediated release of VEGF and PDGF stimulates smooth muscle cell proliferation and vessel wall remodeling—responses that are beneficial during repair but pathogenic in aneurysm expansion and atherosclerotic plaque destabilization." (PMID 41304763, 2025). "We examined the mRNA levels of Mmp2 and Mmp9 in the aneurysm tissue." (PMID 38881898, 2024). "To validate the SMC phenotype modulation hypothesis, we performed multicolor immunofluorescent staining (mIF) to examine marker proteins associated with phenotypic modulation (including α-SMA, MMP-9 and ICAM1) in fusiform aneurysm and cerebral arteries." (PMID 38741091, 2024). "Matrix metalloproteinase-9 (MMP-9) is a calcium-zinc-dependent proteolytic enzyme that degrades almost all components of the extracellular matrix, is involved in the body's inflammatory response, and can accumulate in large amounts around aneurysms." (PMID 38496021, 2024).
aneurysm (continued). "More recently, in an aneurysm model under estrogen-deficient conditions, ERα and SIRT1 depletion may promote the activation of the NLRP3/IL-1β/MMP-9 pathway and enhance intracranial aneurysm rupture leading to SAH." (PMID 36505409, 2022). "MMP2 and MMP9 are known to be pivotal in human aneurysm development." (PMID 33467682, 2021). "Moreover, attenuated aneurysm formation was accompanied by depressed macrophage infiltration and MMP-9 expression." (PMID 33239616, 2020). "Moreover, several lines of evidence indicate that MMPs with a high capacity to degrade collagen, particularly MMP-9, was expressed by infiltrating macrophages as well as resident vascular smooth muscle cells in aneurysm lesions." (PMID 33239616, 2020). "Hence, we examined the in vivo effects of an MMP-9 inhibitor on aneurysm formation in WT, CCl3−/− and Ccr5−/− mice after CaCl2 treatment." (PMID 33239616, 2020). "Moreover, the 3-hydroxy-3-methylglutaryl coenzyme A reductase inhibitor, cerivastatin, has been shown to suppress MMP-9 production in the aortic wall in humans and prevent aneurysm formation in an elastase-induced AAA model in rats." (PMID 31390798, 2019). "In this view, MMP-9 inhibition could represent a novel approach to reduce ectopic calcification, preventing aneurysm rupture." (PMID 28446225, 2017). "Samples taken fromaortic aneurysms demonstrate that MMP-2 activity is relatively lower thanthat of MMP-9, which suggests that expansion in MMP-2 activity could mean anearly event in the temporal evolution of AAA pathogenesis." (PMID 28832801, 2017). "Generally, the increase in MMP-9 activity may be a risk of cerebral vascular abnormality and TIMP-1 has a protective role for aneurysm progression." (PMID 25932641, 2015). "However, few or no macrophages were detected in the aortas, suggesting that VSMCs are responsible for the production of MMP‐9 in the initial stage before aneurysm progression." (PMID 23782924, 2013). "In addition, an early increase in MT1-MMP expression with a subsequent increase in MMP-2 and MMP-9 activity has been observed in Ang II induced aneurysm formation, and MMP-9 production in aortic aneurysms relies on Ang II/ERK pathway." (PMID 23840100, 2013). "Due to their anti-oxidant property, angiotensin-converting enzyme inhibitors have been reported to normalize impaired bradykinin-mediated endothelium-dependent venodilatation in smokers, and inhibition of MMP-9 by doxycycline was useful in preventing aneurysm growth." (PMID 19250534, 2009). "Expression of MMP-9 is elevated in vascular disease, and in particular within aneurysm tissues." (PMID 19580662, 2009). "Thus, MMP-9 activation by chymase might be involved in the progression and rupture of aneurysms via degradation of the matrix of vascular structures." (PMID 36289761, 2022). "MMP9 could destroy elastin and play a role in outward remodeling and aneurysm formation." (PMID 32911750, 2020). "However, besides patterns of blood flow and WSS, degeneration of the extracellular matrix in the arterial wall by upregulation of MMP2 and MMP9 or infiltration of macrophages also have important synergistic effects with hemodynamic status if an aneurysm develops or ruptures." (PMID 24195732, 2013). "In experimental aneurysm models, AT1R blockade suppresses macrophage infiltration, elastin degradation, and aortic expansion in parallel with marked downregulation of Mmp-9 transcripts within the vessel wall." (PMID 41304763, 2025). "The expression of MMP-9 in the aneurysm wall was significantly enhanced, and positive expression of MMP-9 was observed throughout the aneurysm wall." (PMID 40244203, 2025). "Investigation of aneurysm walls revealed significantly lower macrophage infiltration, and Western blots measured lower MMP-2, MMP-9, and NF-κB in resveratrol-treated groups." (PMID 41155344, 2025).
aneurysm (continued). "Aortic VSMCs exposed to IL-1β, or TNF showed increased MMP2 or MMP9 activation mediated by a mechanism involving amplified ERK phosphorylation, thus promoting aneurysm progression." (PMID 39011492, 2024). "The degradation of elastin in aneurysms is primarily mediated by the upregulation of MMPs, particularly MMP-2 and MMP-9, which break down the ECM components, including elastin and collagen." (PMID 39595942, 2024). "Significantly, inflammatory-related markers, such as MMP-9 and ICAM1, exhibited prominent staining within smooth muscle layer of fusiform aneurysm lesions, whereas their expression was scarce in cerebral arteries." (PMID 38741091, 2024). "Upregulation of both MMP-2 and MMP-9, as well as of MMP-1, has been reported in aneurysms of the abdominal aorta." (PMID 39408865, 2024). "Regarding this, a positive correlation between TLR4, MMP9, and MMP2 and aneurysm development has been reported." (PMID 37445606, 2023). "The matrix metalloproteinase (MMP) family, especially MMP-2 and MMP-9, is closely related to the destruction of ECM in aneurysm formation." (PMID 37175712, 2023). "In BS, TNFα results in EC apoptosis and induces the expression of proinflammatory mediators, including metalloproteinases MMP-2 and MMP-9, which are important in ECM destruction and aneurysm formation." (PMID 36834577, 2023). "Monocytes adhesion, migration, and MMP-9 production all increased in AAA patients, leading to aneurysm expansion." (PMID 36698942, 2022). "The highest concentration of the NGAL/MMP-9 complexes was found in the luminal part of the thrombus (compared to abluminal and central ILT layers, aneurysm wall and interface fluid), if normalized to the tissue weight and total protein concentration." (PMID 34572424, 2021). "It was shown that NGAL/MMP-9 complexes were present in the ILT, the interface fluid and the aneurysm wall." (PMID 34572424, 2021). "Specific proteinases dissolve elastic fibers, and MMPs are thought to contribute to aneurysm development, including MMP-2, MMP-9, and MMP-12." (PMID 34123662, 2021). "In their study, the interleukin-1beta (IL-1β), matrix metalloproteinase-2 and matrix metalloproteinase-9 (MMP-2, MMP-9), and nitric oxide synthetase (NOS) in aneurysm wall were all decreased compared to normal artery." (PMID 34847937, 2021). "During aneurysm formation, expression of some MMPs, such as collagenase-1 (MMP-1), gelatinase B (MMP-9) or macrophage elastase (MMP-12) is upregulated." (PMID 33799971, 2021). "The study reported that after two weeks of doxycycline treatment before the aneurysm repair surgery reduces aortic wall MMPs and selectively suppresses neutrophil collagenase and gelatinase (MMP-8 and MMP-9) protein levels." (PMID 34123662, 2021). "Monocyte adhesion, migration, and MMP-9 production are all increased in AAA patients and lead to aneurysm expansion." (PMID 34805319, 2021). "In our previous study, we documented an increase in plasma levels and tissue expression of both MMP-9 and NGAL in patients with central and peripheral aneurysms." (PMID 32111073, 2020). "Physiologically, an aneurysm wall has decreased elastin and increased collagen in its structure, due to the degradation of elastin, mainly by MMP-2 and MMP-9." (PMID 33419373, 2020). "Results from a murine aneurysm model suggested that TNF-α promotes MMP-2 and MMP-9 expression, increasing macrophage infiltration into the aortic tissue, thereby leading to aneurysm formation." (PMID 31989839, 2020). "Elevated levels of MMP-9 and MMP-2 are responsible for the formation and size of aneurysms, as they contribute to the degradation of elastin." (PMID 33419373, 2020). "Upon treatment of AngII-induced aneurysms (TNFα and CaPO4-independent, RANKL-dependent) with RANKL-neutralizing antibody, we observed decreased TRAP and MMP-9 expression." (PMID 31546645, 2019). "MMP9 activity varied with aortic diameter in AAA, and its expression was reported to be elevated in aneurysms with a diameter of 5.0 to 6.9 cm." (PMID 30373522, 2018).
aneurysm (continued). "The expression of MMP9 has been shown to be up-regulated in the vascular wall of human AAA and also in aneurysm tissue in a mouse model of MFS." (PMID 29530068, 2018). "It has been reported that MMPs synthesis and activity are increased in rat and human aneurysm tissue, especially MMP2 and MMP9, which can degrade elastin, resulting in less flexibility and loss of the integrity of the vessel walls." (PMID 28164126, 2017). "MMP-9 and MMP-2, which degrade the extracellular matrix, work in concert to form AAA, and both MMP-9 and MMP-2 knockout mice are resistant to aneurysm development." (PMID 29348704, 2017). "We found that these aneurysm prone factors significantly and concurrently induced HIF-1α, MMP-2 and MMP-9 expression (n = 4–5)." (PMID 27363580, 2016). "Immunofluorescence showed that during aneurysm initiation MMP-2 and MMP-9 were distributed in SMCs, and in situ hybridization indicated that they were transcribed by SMCs." (PMID 24023941, 2013). "This aneurysm showed more infiltration of macrophages and neovascularization in the aortic wall, more upregulation of MMP2 and MMP9 expression in the media, but less elastin content, endothelial recovery and a lower SMC content." (PMID 23844207, 2013). "Patients with BAV and aneurysms ≥55 mm in diameter had considerably higher levels of MMP-8 and MMP-9 in the convex sites than in the concave sites." (PMID 22645456, 2012). "Accordingly, serum MMP-9 levels increase in SAH patients and normalize by day 12 after-SAH, suggesting an intimate relationship between MMP-9 and aneurysm rupture." (PMID 23316103, 2012). "In patients with abdominal aortic aneurysm, doxycycline treatment for one week prior to the repair surgery resulted in decreased MMP-9 and MMP-2 in the wall of the aneurysms." (PMID 15667660, 2005). "Aortic dissection patients manifested even higher MMP-2 (a gelatinase) and MMP-9 levels that non-dissected aneurysm patients." (PMID 39830801, 2025). "Moreover, Ang II-induced overexpression of critical genes involved in aneurysm pathogenesis—such as VEGF, MMP-2, MMP-9, HMGB1, and NF-κB p65—was significantly downregulated following CL treatment." (PMID 40868841, 2025). "For instance, the levels of MMP‐2 and MMP‐9 are significantly elevated in patients with AAA, particularly MMP‐9, which has been shown to degrade collagen and elastin in the ECM, leading to arterial wall weakening and the promotion of aneurysm formation." (PMID 40770945, 2025). "Together with evidence that Ang II induces MMP-9 via NF-κB in vascular smooth muscle and immune cells, these findings support renin–angiotensin blockade as a strategy to recalibrate MMP-9 homeostasis in vascular walls, myocardium, and aneurysm models." (PMID 41304763, 2025). "Increased levels of MMP-9 and MMP-2 are responsible for aneurysm formation." (PMID 37175712, 2023). "Two independent studies demonstrated absence of MMP-9 suppressed aneurysm development in the CaCl2-application model and elastase-induced AAAs." (PMID 37799778, 2023). "However, after 7 days of healing, all humoral inflammation markers examined (TNF-α, IL6, MMP-2, MMP-9 and FGF) were markedly increased in coiled aneurysms." (PMID 37533024, 2023). "Additionally, in rat aneurysm cells, (Matrix Metallopeptidase 2) MMP2 and (Matrix Metallopeptidase 9) MMP9 are involved in aortic aneurysm proliferation and migration." (PMID 34997174, 2022). "The elevated systemic inflammatory status in COVID-19 patients via increasing blood brain barrier permeability can increase MMP-9 and MMP-9 by the dysregulated breakdown of arterial collagen can lead to arterial instability and can consequently result in ICH and aneurysm aSAH." (PMID 36504633, 2022). "In addition, matrix metalloproteinase 9 (MMP9) is activated by TNF-α, which leads to the destruction of elastin and aneurysms formation in the blood vessel wall, and increased NO concentration, which leads to the blood vessel wall's expansion and damage." (PMID 35924269, 2022).